SKIC3 (SKI3 subunit of superkiller complex)
Description:
Component of the SKI complex, a multiprotein complex that assists the RNA-degrading exosome during the mRNA decay and quality-control pathways. The SKI complex catalyzes mRNA extraction from 80S ribosomal complexes in the 3'-5' direction and channels mRNA to the cytosolic exosome for degradation. SKI-mediated extraction of mRNA from stalled ribosomes allow binding of the Pelota-HBS1L complex and subsequent ribosome disassembly by ABCE1 for ribosome recycling. In the nucleus, the SKI complex associates with transcriptionally active genes in a manner dependent on PAF1 complex (PAF1C).
Synonyms: Ski3; KIAA0372; TTC37; THES
Tractability: PROTAC: ubiquitination databases record sites on it.
Gene: Protein-coding gene on chromosome 5 (95,461,755 to 95,555,050, reverse strand). Ensembl gene ENSG00000198677.
Subcellular location: Cytoplasm; Nucleus
Subcellular location (Human Protein Atlas): Nucleoplasm; Cytosol
Pathways (Reactome):
Metabolism of RNA: mRNA decay by 3' to 5' exoribonuclease
Gene Ontology:
Molecular function: protein binding
Biological process: nuclear-transcribed mRNA catabolic process; nuclear-transcribed mRNA catabolic process, 3'-5' exonucleolytic nonsense-mediated decay; rescue of stalled ribosome; RNA catabolic process
Cellular component: cytoplasm; cytosol; euchromatin; nucleoplasm; nucleus; Ski complex
Genetic constraint (gnomAD): Loss-of-function variants: 149 observed, 219.93 expected, observed/expected ratio (o/e) 0.68, 90% interval 0.59 to 0.78. The upper end of that interval is the gene's LOEUF score, 0.78, which puts it in group 3 of 6, group 1 being the genes least tolerant of losing a copy. Missense variants: 1,660 observed, 1,868.5 expected, observed/expected ratio (o/e) 0.89, 90% interval 0.85 to 0.93. Synonymous variants: 607 observed, 667.3 expected, observed/expected ratio (o/e) 0.91, 90% interval 0.85 to 0.97.
Gene-disease validity (ClinGen):
ClinGen rates the evidence that SKIC3 causes each of these diseases.
trichohepatoenteric syndrome 1 (autosomal recessive): Definitive.
Homologues: Orthologues: chimpanzee SKIC3 (99% identical), macaque SKIC3 (97% identical), dog SKIC3 (92% identical), rabbit SKIC3 (90% identical), guinea pig SKIC3 (89% identical), mouse Skic3 (85% identical), rat Skic3 (84% identical), tropical clawed frog skic3 (61% identical), zebrafish skic3 (55% identical), Drosophila melanogaster CG8777 (22% identical).
Diseases named in the same sentence as SKIC3 in open-access papers:
SKIC3 is named in the same sentence as 17 diseases in open-access papers, as found by Europe PMC text mining. Sharing a sentence is not in itself a finding about the gene and the disease. The quoted sentences say what the papers report.
trichohepatoenteric syndrome (7 papers, 2018 to 2025). A severe congenital enteropathy manifesting as intractable diarrhea in the first month of life with failure to thrive and associated with facial dysmorphism, hair abnormalities, and, in some cases, immune disorders and intrauterine growth restriction. "Trichohepatoenteric syndrome (THES) is a genetic disorder caused by autosomal recessive mutations in the SKIC2 or SKIC3 genes that impact the SKI complex, which is essential for RNA surveillance." (PMID 38987716, 2024). "In addition, mutations in SKIC3 cause trichohepatoenteric syndrome, one of the features of which is facial dysmorphism (prominent forehead and cheeks, broad nasal root and wide-spaced eyes)." (PMID 41075272, 2025).
liver disease (2 papers, 2024 to 2025). "In addition, she developed portal hypertension and varices, which are considered uncommon in patients with SKIC3 mutations and were described in one patient with SKIC2 mutations." (PMID 38987716, 2024). "Tricho-hepato-enteric syndrome (THES), a rare autosomal recessive disorder caused by variants in the SKIC3 or SKIC2 gene, is characterized by intractable diarrhea, woolly hair, growth restriction and liver disease." (PMID 40675981, 2025).
glaucoma (1 paper, 2025). Increased pressure in the eyeball due to obstruction of the outflow of aqueous humor. "Notably, tricho-hepato-enteric syndrome 1 attributed to SKIC3 variants, exhibits a higher carrier rate in this population, while CYP1B1-related glaucoma presents with unique hotspot variants." (PMID 40421383, 2025).
hemochromatosis (1 paper, 2025). A disorder of iron metabolism characterized by a triad of HEMOSIDEROSIS; LIVER CIRRHOSIS; and DIABETES MELLITUS. "Here we report a neonatal case of THES with neonatal hemochromatosis, in which the novel compound heterozygous SKIC3 variants NM_014639.4:c.815_816del p.(Gly272AlafsTer9) and NM_014639.4:c.2284G>A p.(Gly762Arg) were identified." (PMID 40675981, 2025). "In conclusion, we report a neonatal case of THES with neonatal hemochromatosis, in which novel compound heterozygous variants in SKIC3 were identified." (PMID 40675981, 2025). "Here, we report a neonatal case of THES with neonatal hemochromatosis, in which novel compound heterozygous variants were identified in the SKIC3 gene." (PMID 40675981, 2025). "No previous cases of THES with hemochromatosis have been confirmed genetically, and the relationship between SKIC3 function and hemochromatosis remains unknown." (PMID 40675981, 2025).
cancer (2 papers, 2009 to 2025). A tumor composed of atypical neoplastic, often pleomorphic cells that invade other tissues. "In MSI-H cancers, PELO is required owing to MSI-H-associated mutations in TTC37 (also known as SKIC3), a critical component of the SKIc." (PMID 39910293, 2025).
SKIC3 also shares sentences with these, for which no sentence is quoted: genetic disorder (2 papers); cerebrotendinous xanthomatosis (1); ectodermal dysplasia (1); enteritis (1); epilepsies (1); Failure to thrive (1); hepatopathy (1); Immunodeficiency (1); infection (1); oral cancer (1); portal hypertension (1); varices (1).